IL6 (interleukin 6)
Diseases named in the same sentence as IL6 in open-access papers (continued):
Sharing a sentence is not in itself a finding about the gene and the disease.
tumor (continued). "The proinflammatory cytokine IL-6 is released by various immune cells triggered by IL-1β and TNF, but also produced by tumor cells directly as also proven for MPM with tumor-promoting effects." (PMID 33562138, 2021). "Immune modulating cytokines (TGF-β, IL-10, IL-17, and IL-23) facilitate tumor development, while others (IFN-γ, TNF-α, GM-CSF, IL-2, IL-6, IL-17, and IL-12) promote immune surveillance and delay its growth." (PMID 34518597, 2021). "After recruitment to the TME, TAMs release different factors—such as VEGF, IL-6, Angiopoietin 2 (ANG2), and insulin-like growth factor-binding protein 1 (IGFBP1)—to stimulate neovascularization in the tumor." (PMID 34503065, 2021). "In BLCA, miR-153 anti-tumor activity was mediated by targeting IDO1, further inactivating IL6/STAT3/VEGF signaling pathway." (PMID 33672684, 2021). "In tumor environment, it has been reported that AST decreased the amount of inflammatory markers such as TNF-α, IL-6, and IFNγ via NFk-B inhibition." (PMID 33509300, 2021). "Some inflammatory factors and proinflammatory cytokines including interleukin-6 (IL-6), IL-1β, and prostaglandin E2 (PGE-2) also promote tumor growth." (PMID 35127500, 2021). "Specifically, tumor-derived PGE2 directly induces the production of cancer-promoting inflammatory mediators, such as IL-6, CXCL1, and G-CSF, by myeloid cells, while preventing the activation of anti-tumor type I immune responses." (PMID 34063828, 2021). "The expansion and activation of MDSCs in the TME are mainly induced by cytokines secreted by tumor cells or activated immune cells, such as VEGF, GM-CSF, M-CSF, G-CSF, IL-1β, IL-4, IL-6, and IFN-γ." (PMID 34527668, 2021). "CAF can produce tumor-promoting cytokines such as CXCL12, IL-6, HIF1a, and TGF-b2, and monocytic MDSCs can promote tumor epithelial to mesenchymal transition (EMT)." (PMID 34831357, 2021). "Studies showed that cytokine signaling, including interleukins (IL) such as IL-6, IL-8, and TNF-α, plays an important role in regulating this process by promoting tumor initiation, growth, and cancer progression." (PMID 34573967, 2021). "Results showed that IL-6/JAK/STAT3 signaling, complement and mitotic spindle were three pathways that mostly enriched in tumor samples." (PMID 34544443, 2021). "In summary, the administration of an extract from A. heterophyllus Lam., standardized to contain 84% (w/v) artocarpin, effectively suppressed tumor multiplicity and inflammation in AOM/DSS-induced mouse colon via decreasing the expression of cytokine Il-6." (PMID 33767225, 2021). "In accordance, addition of exogenous IL-6 suppressed cGAMP-induced type I IFN expression and anti-tumor responses." (PMID 33790360, 2021). "For example, in osteosarcoma, MSCs-tumor cells interplay stimulates TGF-β/Smad2/3 axis in MSCs and generates IL-6, which then autocrinally facilitates the differentiation of MSCs into fibroblasts or pericytes." (PMID 35096289, 2021). "We injected the cells into the IL6−/− mice through tail vein injection to prevent confounding effects from the host IL‐6 and determined the impact of IL‐6 KO in SMAD3‐mediated tumor metastasis." (PMID 34392614, 2021). "Our data showed that gefitinib-treated TNBC cells exhibited enhanced production of proinflammatory cytokines/chemokines such as IL-6, IL-8, and CXCL2, hence increasing the number of tumor-infiltrating immune cells including IL-26-producing cells in the TME." (PMID 34021125, 2021). "IL6 serum levels significantly correlated with disease-free survival and 18F-FDG PET/CT uptake, an indirect measurement of tumour glycolysis and, hence, of acidosis." (PMID 34831016, 2021). "In the tumor microenvironment, inflammatory factors, such as IL-6, TNF-α, and TGF-β, play an important roles in tumor occurrence, development, invasion and metastasis." (PMID 34113572, 2021).
tumor (continued). "Another research observed that both in vitro and in vivo, exosomes derived from heat-stressed tumour cells, which contain abundant HSP70, were more effective at stimulating dendritic cells to secrete IL-6 for converting Tregs into Th17 cells." (PMID 34781996, 2021). "Further evidence of the link between IL-6, OSM and EMP provided by more dynamic studies on primary human tumour explants or patient-derived xenografts (PDXs) would be desirable." (PMID 34361105, 2021). "Inflammatory mediators, such as tumor necrosis factor (TNF)-α, IL-6, IL-10, and TGF-β, participate in tumor initiation and progression." (PMID 33917793, 2021). "Pharmacologic inhibition of SIRT1, required for dimerization of STAT3 downstream of IL-6, reduces Th17 numbers in CRC patients and tumor development in mice." (PMID 34489941, 2021). "Combinatorial induction of IL6 and S100A8/A9 in the TME and ICAM-1 and IL8 in the CDX tumor comprise a positive feedback loop that drives inflammation." (PMID 34010296, 2021). "Our data suggested that the changes in miR101 in the tumor-derived exosomes played an important role in IL1A and IL6 expression in macrophages, although the hypoxic stress did not change the total amount of exosome secretion." (PMID 34362882, 2021). "Expression levels of proinflammatory factors IL-6, IFN-γ, and TNF-α were also increased by CUMS compared with tumor group." (PMID 34650925, 2021). "More specifically, in the MM microenvironment, IL6 and TGF-β produced by MM cells promote Th17 polarization, while IL-17 (also known as IL17A) produced by Th17 cells promotes tumor progression and MMBD." (PMID 33673480, 2021). "After radiotherapy, altered inflammatory cytokines (such as IL-6, IL-10, and TNF) lead to the recruitment of TAMs with a tissue reparative phenotype and contribute to tumor recurrence and metastasis." (PMID 34733785, 2021). "MSCs exposed to PDAC cells are activated into CAF-secreting tumor-promoting proteins such as hepatocyte growth factor (HGF), epidermal growth factor (EGF), and interleukin-6 (IL-6)." (PMID 33803229, 2021). "IL-6 predicted DSS in both Kaplan–Meier analysis (p < 0.001) and multivariate regression analysis, including gender, age and tumor size (HR 4.82; CI 1.96–11.86; p = 0.001)." (PMID 32621022, 2021). "After excision of the tumor, LDH levels (211IU/L) and C reactive protein levels (139 mg/L) increased, while IL-6 (21.54pg/mL) decreased." (PMID 33787583, 2021). "Here we develop a dual-targeting anti-IL-6 and pro-CD40 strategy to reverse Mφ-mediated tumor immunosuppression and to overcome primary tumor resistance to immune checkpoint blockade in GBM." (PMID 34103524, 2021). "The present paper demonstrates that among all of the proteins tested in our investigations, serum M-CSF, CXCL-8, IL-6 and TIMP-1 are better biomarkers than the currently used, well-established classical tumor marker—CEA—in the diagnosis of CRC." (PMID 34071492, 2021). "IL-6/STAT3 pathway suppression, β-catenin suppression, pSmad3C/P21 tumour-signalling suppression, and CD57+ NK recruitment are said to be the underlying mechanisms for the action of IL-37." (PMID 34336101, 2021). "Screening for tumor‐related cytokines, such as TNF‐a, VEGF, bFGF, IL‐1α, and IL‐6, as suggested by previous studies, was performed by an ELISA of collected serum." (PMID 33112032, 2021). "In the tested in vitro system, maximum tumor cytotoxicity (IC99) was reached at a concentration of 155 pM cibisatamab, which approximately corresponds to the EC5 for IL2 and IL6 release." (PMID 34862519, 2021). "Although it is known that tumor-infiltrating immune cells are a primary source of IL-6 production in TME, the mechanism of IL-6 secretion is not fully understood." (PMID 34093869, 2021). "Examples of cytokines and growth factors induced by TLR2 and/or TLR4 in OSCC cells include IL-1, IL-6, GM-CSF, TNF-alpha, CCL2, CCL20, CXCL8, and VEGF, which contribute to the inflammatory environment, vascularization, and tumor cell properties." (PMID 35048056, 2021).
tumor (continued). "In contrast, myeloid-derived suppressive cells (MDSC), pro-angiogenic Type-2 tumor associated macrophages (TAM) and/or their derivative cytokines IL-6, TNF, IL-1β and IL-23 are generally recognized as dominant tumor-promoters." (PMID 34930302, 2021). "Strikingly, our work further shows that this dual-targeting anti-IL-6 and pro-CD40 strategy overcomes GBM resistance to checkpoint blockade therapy, likely due to a shift of tumor immune status from immunologically cold to hot." (PMID 34103524, 2021). "TAMs isolated from C57BL/6 mouse tumour models treated with TSA exhibited decreased expression of the M2 markers Arg-1 and CD206, with heightened expression of the M1 markers iNOS and IL-6." (PMID 34944870, 2021). "The interface between tumour cells and neutrophils raised the manifestation of CXCR-4,7; MMP12,13; TGF-β, IL-6, the metastasis-related genes." (PMID 34336101, 2021). "Herein, we determined the effect of chronic DOX administration on serum levels of the inflammatory markers IL-6 and TNF-α, in juvenile tumor-free and tumor-bearing mice." (PMID 34445729, 2021). "In PDAC, tumor-derived arachidonic acid induces TAMs to produce immunoinhibitory and tumor-supporting molecules such as PGE2, VEGF, monocyte chemoattractant protein-1 (MCP-1), IL-6, and matrix metallopeptidase (MMP)-9." (PMID 34988072, 2021). "Furthermore, IL-6 may cooperate with HER2 in the process of tumor development." (PMID 34458273, 2021). "IL-6 is overexpressed in a variety of cancers, and it can activate the STAT3 signaling pathway to promote tumor occurrence." (PMID 34976805, 2021). "IL6 (Interleukin-6), one of the major cytokines in the TME, has been reported to promote tumor progression including apoptosis, proliferation, invasiveness, and metastasis via regulating multiple key cell signaling pathways." (PMID 35047006, 2021). "Previous studies revealed that IL-6, TGF-β stromal cell-derived factor 1 (SDF-1), RANKL, and CCL2 produced by bone stromal and tumor cells are responsible for this alteration in the attacked bone tissue." (PMID 34868907, 2021). "IL-10 inhibits tumor growth by hindering several inflammatory and angiogenic factors, including vascular endothelial growth factor, IL-1β, TNF-α, and IL-6." (PMID 34361836, 2021). "Pro-inflammatory cytokines such as IL-1α, IL-1β, IL-6, TNF-α were constitutively expressed in tumor microenvironment to facilitate carcinogenesis." (PMID 34379689, 2021). "Stiffness promoted transcription of more than 20 tumor-promoting factors, including FGF, CTGF, and IL6." (PMID 34873170, 2021). "For instance, interleukin-6, which is a major component of SASP, exhibits potential to accelerate tumor cell proliferation." (PMID 34522864, 2021). "Hypoxia stress reduced the secretion of exosomal miR101 from tumor cells, which led to the induction of IL1A and IL6 in macrophages, in turn promoting lung tumor cell growth." (PMID 34362882, 2021). "First, in a series of OS patients, we confirmed the correlation between high circulating levels of IL6 and IL8 and the tumour presence." (PMID 34831016, 2021). "Along with IL-6, CAF-derived LIF has also been identified as a major promoter of suppression in the tumor microenvironment." (PMID 34203869, 2021). "At the same time, both mRNA and protein expression levels of IL6 were up-regulated in THCA tumor tissues by comparing with adjacent normal tissues, and are significantly related to the tumor invasion of THCA." (PMID 33792624, 2021). "Furtherly, the recruited macrophages in turn secret IL-6 to activate JAK2/STAT3 signaling, promoting tumor metastasis." (PMID 34326840, 2021). "After blocking the IL-6/STAT3 pathway, HCC cells co-cultured with macrophages exhibit cell apoptosis, reduced drug resistance, suppressed cell invasion, migration, and tumor formation; all are indicators of the enhanced tumor suppressive function of M1." (PMID 34696292, 2021).
tumor (continued). "Mechanistically, IL-6 mediated the activation of pro-survival signals, especially the JAK/STAT3 signaling pathway, to facilitate tumor growth and distant metastasis." (PMID 34657635, 2021). "This set includes tumor expression of c-Met and serum levels of HGF, IL-6, IL-8, CXCL9, CXCL10 and CXCL11." (PMID 34200459, 2021). "Expression of chemokines for monocytes was low in tumor cells from EGCG-treated mice, decreased IL-6 and Transforming Growth Factor-β (TGF-β) and increased TNF-α." (PMID 34444715, 2021). "Four tumor microenvironment-related genes (CD79A, CXCL13, IL6 and CCL19) were identified as biomarkers for PRCC prognosis." (PMID 33993869, 2021). "Of note, after an observable reduction in tumor growth and metastasis following ITGB4-DC vaccination plus anti-PD-L1 immunotherapy, we found increased serum levels of IFN-γ and IL-6 compared to controls in both the 4T1 and SCC7 models." (PMID 34504657, 2021). "In murine metastatic lung tumor models, MDSCs were found to populate the tissue as early as 2 weeks prior to tumor formation; secrete IL-6, S100A8/A9, VEGF, and IL-10 in order to establish the tumor; and recruit additional MDSCs to the lung." (PMID 34482371, 2021). "In BC the release of TNF-α, IL-6 and IL-1β in the TME sustained M2 macrophages, which boost tumor initiation, dissemination and metastasis formation." (PMID 34354950, 2021). "Constitutive STAT3-binding activity is observed in most human NSCLC cell lines and promotes tumor cell proliferation in response to growth factors (e.g., EGF, HGF) and cytokines (e.g., IL6)." (PMID 34944848, 2021). "These cytokines, including IL-6, TGF-β, VEGF and IL-12, are known for taking part in the malignancy of the tumor, including the invasive, angiogenetic, and immunosuppressive mechanisms." (PMID 34830817, 2021). "M1 macrophages are induced by interferon (IFN)γ and have anti-tumor activity, producing inflammatory cytokines such as interleukin (IL)-1β, tumor necrosis factor (TNF)-α, IL-6, and IL-23." (PMID 34685762, 2021). "Various immunomodulatory cytokines, such as IL4, IL6, and TGF-β, produced by immune cells within the tumor microenvironment promote tumor growth and progression." (PMID 33504001, 2021). "This study proposes a new mechanism, whereby hypoxia elicits inflammation in the tumor microenvironment by inhibiting exosomal miR101, which stimulates IL1A and IL6 expression in macrophages, leading to inflammation." (PMID 34362882, 2021). "In the tumor microenvironment, IL-6/JAK STAT3 signaling contributes to proliferation, invasiveness, and metastasis of tumor cells and strongly inhibits the antitumor immune response." (PMID 33912584, 2021). "IL6 is involved in the STATS-mediated signal transduction pathway by mediating tumor immune suppression, tumor cell survival, premetastatic niche formation, and chemotherapy resistance." (PMID 34804944, 2021). "Within solid tumors, the accumulation of MDSCs within the TME correlates with the presence of tumor-mediated cytokines/chemokines, including IL-6, IL-1, GM-CSF, prostaglandins, and TGF-β, correlated with clinical tumor stage." (PMID 35127700, 2021). "Our data indicated that the triple treatment almost completely blocked tumor growth during the therapy window and, to a lesser extent, combination therapy with IL-6 neutralization and CD40 stimulation markedly reduced tumor growth." (PMID 34103524, 2021). "IL-6, IL-1β and TNF-α are secreted at high levels in and around the tumor environment after the exposure of MNPs, which alters the TME and improves immune response." (PMID 34834282, 2021). "We now report the decreased level of IL-6 in HCC tissues treated by TBK1 antagonist as well as the TBK1 expression in HCC and tumor stroma." (PMID 33679751, 2021). "In mice, 6 weeks of spontaneous PA before liposarcoma injection and 8 weeks of voluntary wheel running post-tumor injection increased IL-6, FABP4, PPAR-γ, autophagy markers, and tumor growth." (PMID 33670492, 2021).
tumor (continued). "These EVs, released in response to cisplatin, can stimulate the migration of MSCs and increase the secretion of IL-6, IL-8, and VEGFA, thus stimulating a more aggressive and tumor-promoting phenotype in MSCs." (PMID 34440886, 2021). "The tumor endothelium also produces a number of anti-inflammatory cytokines including endothelin-1, FGF, TGF-beta, IL-6, IL-8, PDGF, G-CSF, and others." (PMID 35096619, 2021). "To further investigate the mechanisms underlying IL-6-dependent suppression of Bev anti-angiogenic activity, we examined the effects of IL-6 on secretion of the angiogenic modulators VEGF, Ang1/2, and osteopontin by tumor and HUVEC." (PMID 33833265, 2021). "Studies have shown that TGF-β released by tumor cells activated the p38-MAPK pathway in CAFs, increasing the levels of chemokines such as CXCL10, IL-6, and IL-8, thereby inducing glycogen catabolism in tumor cells." (PMID 34512351, 2021). "MDSCs interact with the TME, and tumor and stromal cells secrete TGF-β, MMP9, BV8, IL-6, IL-1β, β-FGF and VEFG through autocrine and paracrine mechanisms, mobilizing and expanding MDSCs and further promoting tumor growth." (PMID 34925375, 2021). "As aberrant IL‐6–JAK–STAT3 signaling is an important mechanism for cancer initiation, development, and progression, S1P/S1PR1 signaling accelerates tumor growth and metastasis via an IL‐6/JAK2‐mediated persistent activation of STAT3." (PMID 34289244, 2021). "In oral squamous cell carcinoma (OSCC), IL6-induced inflammation alters global LINE1 hypomethylation, while also resulting in the hypermethylation of tumor suppressor genes such as CHFR, GATA5, and PAX6." (PMID 34901003, 2021). "Previous works also indicated that metastatic melanoma cells secrete a large amount of TNF-α, IL-6, IL-12, IFN-γ, VEGF, eotaxin, and RANTES, triggering a cascade of effects that include the increase of MMP-2 enzymatic activity and tumor cell aggressiveness." (PMID 33466236, 2021). "Mechanistically, LPC downregulates the Gal-3/Gal-3BP/IL6 axis between NB cells and iBMSC in an NQO1-dependent manner, thereby inhibiting the tumor-promoting effect of iBMSC-derived IL6 on NB cells." (PMID 34790130, 2021). "In CRC tissues, CAFs are important sources of IL-6, which enhances VEGF production, whereby inducing tumor angiogenesis." (PMID 34660589, 2021). "Tumor derived PCs inhibit CD4+ T cell proliferation and activation while promoting CD4+ T cell anergy in vitro, which is also regulated by RGS5- and IL-6-dependent signaling pathways (process ➃)." (PMID 34179005, 2021). "Based on these results, we develop dual-targeting anti-IL-6 and pro-CD40 strategy to activate tumor immunity, sensitizing tumor to T-cell-based immunotherapies including checkpoint blockade." (PMID 34103524, 2021). "H&E staining revealed significant inflammatory cell infiltration and intramucosal tumor in the colon of the AOM/DSS group, and the mRNA levels of inflammatory cytokines (IL-1β, IL-6, and TNF-α) were significantly increased." (PMID 33708251, 2021). "For example, the IL6–JAK–STAT3 pathway, which is involved in the proliferation, survival, invasiveness and metastasis of tumour cells and suppresses the antitumour immune response in TME, had high pathway activity in the low-purity group." (PMID 35083216, 2021). "The GBM microenvironment, particularly through the release of IL-6 and the expression of PD-L1 and IDO-1, has been shown to induce the formation of regulatory T cells (Tregs) that blunt the anti-tumor T cell response." (PMID 34778089, 2021). "Several cytokines including IL-6 promote the stemness of the LUSC cells in the tumor microenvironment and assist the tumor cells to escape immune surveillance." (PMID 33428598, 2021). "In order to evaluate the spatial intratumoral pattern of IL6 and BCL3 expression in ESCC, we used three to six tumor biopsies from different regions of the tumoral mass and two fragments of non-tumoral surrounding tissue, from five patients with ESCC." (PMID 34422669, 2021).